NANOS1 (nanos C2HC-type zinc finger 1)
Description:
May act as a translational repressor which regulates translation of specific mRNAs by forming a complex with PUM2 that associates with the 3'-UTR of mRNA targets. Capable of interfering with the proadhesive and anti-invasive functions of E-cadherin. Up-regulates the production of MMP14 to promote tumor cell invasion.
Synonyms: NOS-1; NOS1; EC_Rep1a; SPGF12; ZC2HC12A
Tractability: PROTAC: ubiquitination databases record sites on it.
Gene: Protein-coding gene on chromosome 10 (119,029,714 to 119,033,730, forward strand). Ensembl gene ENSG00000188613.
Subcellular location: Cytoplasm, perinuclear region; Cytoplasm
Subcellular location (Human Protein Atlas): Cytosol; Nucleoplasm
Gene Ontology:
Molecular function: enzyme activator activity; protein binding; mRNA binding; translation repressor activity; RNA binding; zinc ion binding
Biological process: cell migration; epithelial cell migration; mRNA destabilization; negative regulation of translation; post-transcriptional regulation of gene expression; oogenesis
Cellular component: cytoplasm; cytosol; perinuclear region of cytoplasm
Genetic constraint (gnomAD): Loss-of-function variants: 1 observed, 1.24 expected, observed/expected ratio (o/e) 0.81, 90% interval 0.23 to 1.87. That is too few expected variants to judge how well the gene tolerates losing a copy. Missense variants: 506 observed, 249.1 expected, observed/expected ratio (o/e) 2.03. Synonymous variants: 242 observed, 132.16 expected, observed/expected ratio (o/e) 1.83, 90% interval 1.64 to 1.97.
Homologues: Orthologues: chimpanzee NANOS1 (99% identical), macaque NANOS1 (97% identical), dog NANOS1 (91% identical), pig NANOS1 (90% identical), guinea pig NANOS1 (77% identical), mouse Nanos1 (76% identical), rat Nanos1 (76% identical), zebrafish nanos1 (29% identical), Drosophila melanogaster nanos (19% identical), Caenorhabditis elegans nos-1 (15% identical), Caenorhabditis elegans nos-2 (13% identical). Paralogues in human: NANOS3 (16% identical), NANOS2 (16% identical).
Diseases named in the same sentence as NANOS1 in open-access papers:
NANOS1 is named in the same sentence as 21 diseases in open-access papers, as found by Europe PMC text mining. Sharing a sentence is not in itself a finding about the gene and the disease. The quoted sentences say what the papers report.
infertile (6 papers, 2013 to 2025). "We also found that the infertility-associated p.[(Pro34Thr);(Ser83del)] mutation causes NANOS1 to functionally switch from being anti-apoptotic to pro-apoptotic in the human male germ cell line." (PMID 32344590, 2020). "Thus far, NANOS1 is the only component of germ granules for which a variant causing human infertility has been identified." (PMID 41107697, 2025). "The functional switch of NANOS1 from anti-apoptotic to pro-apoptotic may represent the mechanism underlying the infertility in patients with the NANOS1 p.[(Pro34Thr);(Ser83del)] mutation." (PMID 32344590, 2020). "Therefore, the question arises as to whether such a variant induces remodelling of CB and, if so, whether such remodelling contributes to infertility caused by that NANOS1 variant." (PMID 41107697, 2025). "Moreover, when this NANOS1 gene mutation was tested in a hPGCs model, TCam-2 cell line, it resulted in a functional switch of NANOS1 from anti-apoptotic to pro-apoptotic, providing an explanation of the infertility phenotype of the patients." (PMID 35743036, 2022). "The importance of NANOS1 and NANOS3 for human fertility was demonstrated by identification of mutations in those genes in infertile patients." (PMID 35743036, 2022). "This search revealed that in the case of NANOS1 overexpression, three infertility related genes (CREBBP, CCNB1, and NPAS2) and five cancer-germ cell genes (CENPL, ERCC6L, KIF18A, SIAH1, and TRIM71) were present in three clusters." (PMID 35743036, 2022). "We identified 26 and 52 infertility genes downregulated as well as 28 and 53 cancer-germ cell genes downregulated for NANOS1 and NANOS3, respectively." (PMID 35743036, 2022). "Although mutations in NANOS1 and NANOS3 are associated with pathology of germ cells resulting in infertility, the underlying molecular mechanism of the function of NANOS proteins in the context of human germ cell development and biology remains elusive." (PMID 35743036, 2022). "Since we have identified cell cycle related functions as a common theme for both infertility and cancer-germ cell genes downregulated by NANOS1 and NANOS3, we sought to interrogate the functional relationship between them." (PMID 35743036, 2022). "Eight single nucleotide polymorphisms (SNPs) in CYP26B1, NANOS1 and STRA8 genes were determined by TaqMan allelic discrimination assay in 719 idiopathic infertile men and 383 healthy controls." (PMID 23320086, 2013). "While disruption of NANOS2 and NANOS3 in mice causes infertility, NANOS1, although expressed in germ cells, does not seem to play a significant role in reproduction or other processes in mouse physiology." (PMID 41107697, 2025). "Finally, many of these infertility and cancer-germ cell genes are present together in cell cycle related clusters downregulated by NANOS1 and NANOS3, suggesting a potential role of NANOS-mediated regulation of cell cycle process for proper human germ cell development and fertility." (PMID 35743036, 2022). "Our study provides the first transcriptomic characterization upon induced expression of NANOS1 and NANOS3 in a human germ cell model with an emphasis on mRNAs related to infertility and cancer, many of which carry out functions related to the cell cycle." (PMID 35743036, 2022). "Interestingly, many of these genes are involved in the cell cycle, i.e., 10/26 (34%) NANOS1 and 15/52 (27%) NANOS3 infertility genes as well as 9/28 (32%) NANOS1 and 19/53 (36%) NANOS3 cancer-germ cell genes are cell cycle related." (PMID 35743036, 2022). "Unlike Nanos2 and Nanos3 knockout resulting in mice infertility, Nanos1 knockout mice are viable and fertile, indicating that the NANOS1 protein is dispensable for mouse development and fertility." (PMID 32344590, 2020). "Specifically, to determine whether NANOS1 plays a crucial role in human fertility, researchers examined the same group of infertile males for non-obstructive azoospermia or oligozoospermia, as described for variants of the NANOS1 gene." (PMID 41107697, 2025).
infertile (continued). "Previously, we described a human NANOS1 p.[(Pro34Thr);(Ser83del)] mutation associated with the absence of germ cells in seminiferous tubules of infertile patients, which might suggest an anti-apoptotic role of human NANOS1." (PMID 32344590, 2020).
breast carcinoma (3 papers, 2024). "Among the 1,200 differentially expressed genes, NANOS1 is the only gene whose protein levels are associated with breast cancer prognosis and are downregulated." (PMID 39927118, 2024). "In this study, we analyzed the expression of NANOS1 in breast cancer and found that lower NANOS1 expression in breast cancer patients was associated with a better prognosis." (PMID 39927118, 2024). "Among the top six ranked drugs, nandrolone phenylpropionate and daunorubicin have been previously shown to be effective in treating breast cancer, suggesting that NANOS1 is a novel target for these drugs." (PMID 39927118, 2024). "Indeed, Kaplan–Meier (KM) analysis of breast cancer patients, using median expression of NANOS1, PUM2, AND CPFS4 as a signature, revealed significant stratification of distant metastasis-free survival (DMFS) in patients with the basal subtype." (PMID 39390150, 2024). "Thus, NANOS1 is not only a potential regulatory factor in the onset and progression of breast cancer but also represents a novel therapeutic target." (PMID 39927118, 2024). "The findings identified NANOS1 as a potential prognostic marker for breast cancer." (PMID 39927118, 2024). "Indeed, Kaplan-Meier (KM) analysis of breast cancer patients grouped by subtype and using median expression of NANOS1, PUM2, AND CPFS4 as a signature, revealed significant stratification of distant metastasis-free survival (DMFS) in patients with the basal subtype." (PMID 38410477, 2024). "At the mRNA level, reduced NANOS1 expression was also positively correlated with OS (p < 0.001), RFS (p < 0.001), and DMFS (p < 0.001) in breast cancer patients." (PMID 39927118, 2024). "Recent studies have suggested that NANOS1 expression, a key factor in epithelial-mesenchymal transition (EMT), plays a pivotal role in the invasiveness, migratory potential, and stem cell-like properties of breast cancer cells." (PMID 39927118, 2024). "Additionally, using each gene list as a signature for KM analysis revealed that Nanos1-, Pum2-, and Cpsf4-responsive genes stratify DMFS for patients with the HER2-enriched subtype of breast cancer." (PMID 39390150, 2024). "Additionally, when grouping patients by subtype and using each gene list as a signature for KM analysis, NANOS1-, PUM2-, and CPSF4-responsive genes stratified DMFS for patients with the HER2-enriched subtype of breast cancer." (PMID 38410477, 2024). "Based on these findings, we hypothesized that the direct regulation of the Smarcd1 transcript by NANOS1, PUM2, and CPSF4 may be necessary for the metastasis of breast cancer cells." (PMID 38410477, 2024). "Based on these findings, we hypothesized that NANOS1, PUM2, and CPSF4 may also serve as metastasis modifiers in breast cancer cells." (PMID 38410477, 2024).
Azoospermia (2 papers, 2014 to 2025). Absence of any measurable level of sperm,whereby spermatozoa cannot be observed even after centrifugation of the semen pellet. "NANOS1 and NANOS2 seem to be mainly involved with male germ cell development and maintenance, and indeed NANOS1 mutations have been associated with male infertility manifested as nonobstructive azoospermia or oligozoospermia." (PMID 25054146, 2014).
male infertility (2 papers, 2013 to 2014). The inability of the male to effect fertilization of an ovum after a specified period of unprotected intercourse. "The precise mechanism of the variants of NANOS1 in male infertility needs further investigation." (PMID 23320086, 2013).
triple-negative breast carcinoma (2 papers, 2024 to 2025). An invasive breast carcinoma which is negative for expression of estrogen receptor (ER), progesterone receptor (PR), and human epidermal growth factor receptor 2 (HER2). "In the triple-negative breast cancer cell lines MDA-MB-231 and 4T1, siRNA interference, Dig, and AA treatments effectively downregulated the expression of NANOS1." (PMID 39927118, 2024).
asthma (1 paper, 2018). "Several studies showed that NOS1 gene polymorphism was associated with asthma, OTP played an essential role in the specification of neuronal cell lineages in the developing hypothalamus and NANOS1 was required for maintaining oocyte production." (PMID 29416711, 2018).
cardiac hypertrophy (1 paper, 2023). "Candidate gene identification analyses of exercise-induced cardiac hypertrophy identified five potential regulatory transcripts: IL31ra, Fam167b, Tafa5, Crip3, and Nanos1 (p < 0.01)." (PMID 37178122, 2023).
eye cancers (1 paper, 2022). "Although it is not clear how CDH1 expression results in a decrease in NANOS1 level, this negative correlation between NANOS1 and CDH1 expression on RNA level is observed also in multiple cancer cell lines, representing breast, colon, brain, skin, and eye cancers." (PMID 36012673, 2022).
lung carcinoma (1 paper, 2021). "NANOS1 was up-regulated in lung cancer, and promoted the progress of tumor progress." (PMID 34721973, 2021).
oligoasthenoteratozoospermia (1 paper, 2021). A form of male infertility that is characterized by a combination of low number or oligozoospermia, poor motility or asthenozoospermia, and abnormal shape or teratozoospermia of sperms. "Mutations in the gene NANOS1 are associated with spermatogenic failure and oligoasthenoteratozoospermia." (PMID 33568072, 2021).
retinoblastoma (1 paper, 2018). A malignant tumor that originates in the nuclear layer of the retina. "Interestingly, ectopic expression of NANOS1 was found to be required for growth of human retinoblastoma tumor suppressor-deficient tumor cells." (PMID 29511022, 2018).
testis cancers (1 paper, 2022). "Our bioinformatic analysis of publicly available expression datasets for cancer (TCGA) and normal tissues (GTEx) showed that NANOS1 is overexpressed in a variety of human cancers, including brain, kidney, liver, lung, ovary, pancreas, skin, thyroid gland uterus, and testis cancers." (PMID 36012673, 2022). "To address this, we analyzed the correlation between NANOS1 and NANOS3 with its upstream transcriptional program in human primordial germ cells including transcription factors PRDM1, SOX17, TFAP2C, and PRDM14 expression in testis cancer samples." (PMID 36012673, 2022).
tumor (7 papers, 2018 to 2025). "Therefore, it is likely that in addition to playing a role in germ cell development, NANOS1 downregulates the expression of tumor-suppressing factors, as has already been suggested for other RNA-binding proteins." (PMID 32344590, 2020). "In both 6DT1 and 4T1 cell lines, KD of NANOS1, PUM2, and CPSF4 did not consistently affect primary tumor growth but did significantly reduce the number of metastatic nodules on the lungs compared to shScramble control (shScr)." (PMID 38410477, 2024).
cancer (4 papers, 2022 to 2025). A tumor composed of atypical neoplastic, often pleomorphic cells that invade other tissues. "And the expression level of DLL4 was significantly suppressed in TTN-deficient cancer cells after NANOS1 knockdown." (PMID 41326912, 2025). "Given that immune infiltration levels are linked to cancer progression and treatment outcomes, we further explored the correlation between NANOS1 expression and immune infiltration." (PMID 39927118, 2024). "Regardless, these studies link the overexpression of NANOS1 to the high susceptibility of metastasis by increasing the invasiveness of cancer cells." (PMID 36012673, 2022). "The first report for the potential role of NANOS proteins in various types of cancer was published regarding the correlation between the expression of NANOS1 and tumor suppressor gene CDH1-encoding Epithelial cadherin (E-cadherin)." (PMID 36012673, 2022). "pySCENIC transcription factor analysis of single-cell transcriptomes revealed that NANOS1, a transcription factor, was significantly enriched in TTN-deficient cancer cells with high DLL4 expression." (PMID 41326912, 2025). "The correlation between NANOS1 expression and immune cell infiltration levels in BRCA-BASAL was assessed, given the association of immune infiltration with cancer development and treatment outcomes." (PMID 39927118, 2024). "Although this study demonstrates that miR-127 also downregulates other genes that are overexpressed in cancer, such as FOXO6, SOX11, SOX12, and FASN, it provides the first example that targeting NANOS1 could be a potential cancer treatment strategy." (PMID 36012673, 2022). "Using specific antisense oligos targeting NANOS1 in cancers which it is overexpressed is required to explore whether this could be a viable approach." (PMID 36012673, 2022). "This study suggests that KDM2A overexpression enhances cancer progression and metastasis by downregulating HDAC3, which in turn results in the overexpression of NANOS1." (PMID 36012673, 2022). "Importantly, many of NANOS1 and NANOS3 target mRNAs represent genes previously identified as important factors for fertility as well as cancer-germ cell related genes." (PMID 35743036, 2022). "Moreover, in contrast to NANOS1, NANOS3 is not expressed in normal tissues except in testis and brain tissues, suggesting that it could be used as a marker for a broad range of cancers and, thus, is an attractive gene for diagnostic purposes in the future." (PMID 36012673, 2022).
infection (1 paper, 2024). The state of being infected such as from the introduction of a foreign agent such as serum, vaccine, antigenic substance or organism. "In contrast, the eomesodermin (EOMES) gene is overexpressed, and nucleoside diphosphate kinase A (NME1), polycystic kidney disease 1-like 3 (PKD1L3), as well as nanos homolog 1 (NANOS1) are down-regulated in the infection group." (PMID 38474155, 2024).
NANOS1 also shares sentences with these, for which no sentence is quoted: mammary cancer (3 papers); heart disease (1); oligodendroglioma (1); Sertoli Cell-Only Syndrome (1); small cell lung carcinoma (1); spermatogenic failure (1).